CCL2 (C-C motif chemokine ligand 2)
Diseases named in the same sentence as CCL2 in open-access papers (continued):
Sharing a sentence is not in itself a finding about the gene and the disease.
colitis (continued). "Lactobacillus reuteri 23272 can also attenuate the effects of stressor exposure on pathogen-induced colitis by downregulating the chemokine CCL2, which was proven to be indispensable in Citrobacter rodentium-induced colitis." (PMID 36819028, 2023). "TCRδ-/- mice with colitis had significantly increased expression of these four genes, while only Ccl2 was significantly increased in C57BL/6 mice with colitis albeit to a lesser degree than TCRδ-/- mice." (PMID 37063825, 2023). "In our model of colitis we found the expression of chemokines such as CCL2 and CCL3 and infiltration of neutrophils was decreased in b2KO mice." (PMID 36440681, 2023). "It has been reported that FBXW7 plays a key role in regulating colitis by inducing CCL2 and CCL7 expression in macrophages and promoting the accumulation of pro-inflammatory mononuclear macrophages." (PMID 35419455, 2022). "The secondary BAs consistently showed a significant reduction in the mRNA levels of pro-inflammatory cytokines (Il6, Il1β, Tnfα) and some monocytes-related chemokines (Ccl2, Ccl7, Ccl8) in colitis mice." (PMID 36050867, 2022). "Specifically, neutrophils, not monocytes, represent the predominant leukocyte recruited to the brain during acute colitis, and the resulting adhesive interactions with the cerebral endothelium drives an increased expression of CCL2 and IL-1β in the brain." (PMID 35379260, 2022). "In a dextran sulfate-induced colitis, there was negative regulation of CCL2 expression after treatment with BCP45." (PMID 36357780, 2022). "The concentrations of proinflammatory cytokines IL-1β, IL-6, and CCL-2 in the colonic tissues of colitis mice decreased significantly, while anti-inflammatory cytokines IL-33 and IL-10 increased significantly." (PMID 34567209, 2021). "Among these analytes upregulated in colitis, the levels of G-CSF, CCL2, and CXCL2 were significantly reduced in mice on the ArgHIGH diet in the DSS model." (PMID 30972302, 2019). "Further studies revealed that stressor-induced C. rodentium colitis was C-C motif chemokine ligand 2 (CCL2)-dependent." (PMID 29725324, 2018). "PSMP was up-regulated in the initial stage prior to IL-6, TNF-α and CCL2 up-regulated expression in DSS colitis and promoted the M1 macrophages to produce CCL2." (PMID 28698550, 2017). "In this study, PSMP increases were observed in the initial stage in the DSS-induced colitis model; at this time, CCL2, IL-6 and TNF-α were still expressed at low level." (PMID 28698550, 2017). "PSMP is up-regulated in the initial stage prior to IL-6, TNF-α and CCL2 up-regulated expression in DSS colitis and promote the M1 macrophages to produce CCL2." (PMID 28698550, 2017). "Many of the inflammatory cytokines attenuated by FFAR2 and FFAR3, including C5, CCL1, CCL2, GM-CSF, IL-1α, IL-1β, ICAM-1 and TNF, are associated with colitis." (PMID 27667443, 2016). "However, and in contrast, the DSS-induced colitis caused significantly increased levels of CXCL1, CCL2, CCL3, CCL11, G-CSF, and GM-CSF in Mcpt-4ΔCre mice as compared to Mcpt-4fl/fl mice." (PMID 40697820, 2025). "In this study, we demonstrated that the loss of VDUP1 enhanced macrophage infiltration in DSS-induced colitis, which was accompanied by a significant increase in the mRNA expression of macrophage-attracting chemokines, including CCL2, CCL3, and KC in inflamed colon tissues." (PMID 37686390, 2023). "Additionally, we observed an increase in expression of Nox2 and Ccl2 suggesting macrophages are actively involved in damaging the lungs of TCRδ-/- mice with colitis." (PMID 37063825, 2023). "Moreover, L. acidophilus NCFM and FAHWH11L56 showed similar effects on various indicators of DSS-induced colitis, increasing the IL-10 and IL-17 in the colon, and modifying the CCL2/CCR2 axis and CCL3/CCR1 axis." (PMID 36499169, 2022).
colitis (continued). "After 7 days of induced colitis, upregulation of the expression of 22 genes (Ccl2, Ccl3, Ccl4, Ccl5, Ccl6, Ccl7, Ccl12, Ccl17, Cxcl1, Cxcl2, Cxcl6, Cxcl9, Cxcl11, Ccr1, Ccr2, Ccr3, Ccr5, Ccr8, Cxcr2, Csf3, Osm, and Spp1) was observed in the CβG− group compared to the HβG- control group." (PMID 35163326, 2022). "In addition, we found that curcumin promoted the release of the anti-inflammatory cytokines IL-10 and IL-33 in colitis mice and inhibited the secretion of the proinflammatory cytokines CCL-2, IL-1β, and IL-6." (PMID 34567209, 2021). "CR dose-dependently down-regulated Nlrp3, IL-1β, IL-6, Tnf-α and Ccl2 mRNA levels in colitis mice." (PMID 34393786, 2021). "We found that there were 15 analytes upregulated in both DSS and C. rodentium colitis, including innate immune cell-associated cytokines (G-CSF, IL-1β, TNF-α, LIF, and IL-6), chemokines (CCL2, CCL5, CCL11, CXCL2, CXCL8, CXCL9, MIP-1α, and MIP-1β), and Th1 (IFN-γ) and Th17 (IL-17) cytokines." (PMID 30972302, 2019). "The positive correlation between CCL2 and EC suggests that the gene expression of CCL2 might be a good marker of colitis." (PMID 29890681, 2018). "Because we found that the up-regulated expression of PSMP was earlier than CCL2 in DSS-induced mouse colitis, we explored whether PSMP regulated CCL2 expression in monocytes or macrophages." (PMID 28698550, 2017). "Interestingly, PSMP increases were observed in the initial stage in the DSS-induced colitis model; at this time, CCL2, IL-6 and TNF-α were still expressed at low level." (PMID 28698550, 2017). "We hypothesized that PSMP was up-regulated in the CECs and paracrine to promote the CCL2 expression in M1 macrophages in colitis." (PMID 28698550, 2017). "In contrast, significance of CCL2/CCR2 in colitis models has been established." (PMID 24714157, 2014). "In addition to the CLS, the increase in activated CD4+ T cells in colitis + HFD mice leads to increased MCP-1/CCL2 release in this tissue, which induces migration and activation of macrophages that originate from the CLS and enhance inflammation." (PMID 22073943, 2011). "Similarly, perivascular macrophages in the gut were found to be able to secrete CCL2 in a model of colitis, suggesting that CCL2 production during tissue inflammation may be a shared feature of perivascular macrophage subsets." (PMID 40313955, 2025). "A study indicated that increased levels of CCL2 in macrophages could promote colitis." (PMID 39273257, 2024). "The WT mice that were reconstituted with Drd5−/− bone marrow were more prone to DSS-induced colitis with greater body weight loss, a higher DAI score, shorter colons, and more infiltrating inflammatory cells as well as higher levels of TNFα, IL-6, and CCL2 in serum." (PMID 34884737, 2021). "In our work, the defect of Mcpt-4 gene led to colitis mice producing higher levels of chemokines especially CXCL1, CCL2, CCL3, and CCL11." (PMID 40697820, 2025). "The proinflammatory roles of CCL2 and its key receptor CCR2 have also been reported in colitis models." (PMID 40749055, 2025). "A reduction in CCL2 and TNF‐α production was observed after oral administration of a butyrate derivative in mice with colitis." (PMID 36459573, 2023). "CCL2, CCL8, and CXCL10 have been described to recruit inflammatory monocytes and macrophages or Th1 cells to promote colitis, respectively." (PMID 35463017, 2022). "The increased IL-1b and TNF serum levels and enhanced HIF-1 and IL-10 expression in colitis mice were suppressed by CYN therapy, and the treatment facilitated IL-4, CCL2, and PPARγ expression." (PMID 36278202, 2022). "HHT alleviated DSS-induced colitis with downregulated TNF-α, IL-1β, IL-6, and CCL2 expression; reduced activation of nuclear factor-kappa B (NF-κB) signaling; and diminished proportion of recruited macrophages in colon tissues." (PMID 36211988, 2022).
colitis (continued). "TNF-α as well as CCL2 are also relevant in pathogenesis of IBD as they are released by MC during early stages of inflammation and needed for sustaining colitis." (PMID 35163137, 2022). "This was accompanied by lower production of colonic inflammatory cytokines (i.e., Nlrp3, IL-1β, IL-6, Tnf-α and Ccl2, REV-ERBα target genes) in colitis mice dosed at ZT10." (PMID 34393786, 2021). "This is accompanied by lower production of colonic inflammatory cytokines (i.e., Nlrp3, IL-1β, IL-6, Tnf-α and Ccl2, all these are REV-ERBα target genes) in ZT10-treated than in ZT2-treated colitis mice." (PMID 34393786, 2021). "Of these, CCL2 is known to be an important ligand for CCR2, though its role in colitis is unclear, as DSS treated Ccl2−/− mice have been shown to develop either exacerbated or ameliorated colitis." (PMID 30542349, 2018). "Here, we demonstrated that PSMP was expressed in the colonic mucosa of patients with colitis and significantly up-regulated in the initial stage prior to the expression of IL-6, TNF-α and CCL2 in a DSS-induced colitis in mice." (PMID 28698550, 2017). "Simultaneously, cytokines, including PSMP, IL-6, CCL2, TNF-α, IFN-γ and IL-10 in the colon homogenates were measured with CBA in the time-course study of colitis." (PMID 28698550, 2017). "PSMP overexpression in the colon aggravated the DSS-induced colitis and the anti-PSMP neutralizing antibody mollified the colitis by reducing macrophage infiltration and inhibiting the expression of IL-6, TNF-α and CCL2." (PMID 28698550, 2017). "IL-6, CCL2, TNF-α, and IFN-γ in the mIgG-treated colitis group were extremely elevated and significantly decreased in the 3D5-treated colitis group." (PMID 28698550, 2017). "In line with the morphological appearance of colitis in the knockout mice, the expression of proinflammatory cytokines and chemokines, including IL6, IL1β, Cxcl1, and Ccl2, are dramatically increased in the colonic epithelial cells of the knockout mice." (PMID 28296893, 2017). "Therefore, we sought to determine whether and when PSMP or CCL2 are up-regulated during colitis." (PMID 28698550, 2017). "Real time RT-PCR quantitation confirmed that pro-inflammatory cytokines and chemokines (CCL2, IL-1β, IL-6, IL-23, TNF-α, IL-17A and IL-17F) were elevated in quiescent and active colitis biopsies." (PMID 27271344, 2016). "Our current study showed that direct stimulation of a cell line of colonic epithelial cells with IL-25 increased expression of IL-6, TNFα, as well as IL-8 and CCL2, providing a potential mechanism by which IL-25 contributes to DSS-induced colitis." (PMID 25937893, 2014). "Along with the higher number of immune cells in the colitis + HFD group, we found overexpression of TNFα, IL-6 and MCP1/CCL2 compared to the other three groups." (PMID 22073943, 2011). "Conditional deletion of Ccl2 in BM‐MSCs, but not in colon‐resident MSCs, ameliorated colon inflammation and restored body weight after colitis." (PMID 41309504, 2026). "Our discovery of the remote immunomodulatory role of BM‐MSC‐mobilizing monocytes via CCL2 during colitis without directly influencing local macrophage polarization‐provides a potential mechanistic link between systemic inflammation and localized fibrosis." (PMID 41309504, 2026). "Additionally, in colitis models, CCR2 and CD30L expression in monocytes are positively correlated; CD30L drives monocyte homing and differentiation via the CCL2/CCR2 axis and NF-κB pathway, enhancing inflammation." (PMID 39850880, 2024). "Importantly, we found that growth factors (GFs) like VEGF, IGF, and PDGF as well as chemo-cytokines CCL2, CCL3, CCL4, CCL5, and CCL20 were significantly upregulated in colitis’s colonic tissues." (PMID 37691056, 2023). "The activation of LXRs in a mouse colitis model can suppress the expression of inflammatory factors such as IL-1β, IL-6, IL-17A, TNFα, and chemokines such as CXCL1/KC, CXCL2/MIP2, CXCL8/IL-8, CCL2/MCP1 and CXCL10 in the colon tissue." (PMID 37720208, 2023).
colitis (continued). "TLR4 is a Toll-like receptor and has been reported to have a repairing effect on DSS-induced intestinal injury and up-regulation of IL6, CCL2 and CSF3, which may also be related to their therapeutic effects on TNBs-induced colitis." (PMID 35831878, 2022). "Moreover, the high dose of CYN reduced the expression of IL-17 and HIF-1αin the colon samples from colitis mice, whereas it facilitated the protein abundance of PPAR-γand CCL2." (PMID 36278202, 2022). "The results showed that QYJD could reduce the content of chemokines CCL2 and CXCL2 in colonic tissue of mouse models of colitis induced by DSS." (PMID 36523417, 2022). "Patients with IBD have increased CCL2 expression level, and CCL5 attracts CCR1 and CCR5-expressing inflammatory cells into colon tissue of trinitrobenzene sulphonic acid (TNBS)-induced colitis mice model." (PMID 36518763, 2022). "Importantly, the concentrations of CCL-2, IL-1β, and IL-6 were significantly downregulated after DSS-induced colitis mice were treated with curcumin; IL-33 and IL-10 were significantly upregulated." (PMID 34567209, 2021). "In the current study, we detected a significantly higher colonic expression of Ccl2, Cxcl1, Cxcl2, and Cxcr3 genes in the control and RB groups (p < 0.05, RB vs. control) compared to the FRB group, which supports the protective effect of FRB in colitis." (PMID 28703759, 2017). "In addition, a study demonstrated that there were significantly enhanced gene and/or protein expression of chemokines CCL2 and CCL7 in colitis patients." (PMID 28698550, 2017). "PSMP might trigger the earlier-arriving Ly6ChiCCR2+ monocyte migration from the circulation into the tissue and synergize with CCL2 and CCL7 to promote colitis." (PMID 28698550, 2017). "Because we found that the up-regulated expression of PSMP in DSS-induced mouse colitis was earlier than CCL2, we hypothesized that PSMP was up-regulated in the CECs and paracrine to promote the CCL2 expression in M1 macrophages in colitis." (PMID 28698550, 2017). "In the case of colitis, the potential for R243 to block both CCL2 (MCP-1)/CCR2-driven chemotaxis and CCL1 might enhance the anti-inflammatory effect in comparison with that of CCR8-/- mice." (PMID 24714157, 2014). "In our study, the increase in adipose tissue inflammation seen in the Colitis + HFD group was confirmed by the increase in CLS, activated macrophages, lymphocytes and neutrophils and the overexpression of adhesion molecules, TNFα, IL-6, MCP1/CCL2 and TLR4." (PMID 22073943, 2011). "In addition, DSS-induced colitis mice treated with TcES showed a significant increase in the production of IL-4 and the chemokine MCP-1 (CCL2), along with increased production of IL-22 and IL-31, both of which are cytokines involved in protecting the epithelial barrier." (PMID 40576745, 2025). "Therefore, we suggest that the absence of CCR2 interferes with the development of colitis in mice lacking the receptor for IL10 without altering the expression of its ligand CCL2." (PMID 35013585, 2022). "Therefore, blocking the signal transmission in CCL2/CCR2 axis and CCL3/CCR1 axis might be an important method for L. acidophilus FAHWH11L56 to potentially relieve colitis." (PMID 36499169, 2022). "For L. acidophilus FGSYC48L79, although it blocked the CCL2/CCR2 axis, it can promote the signal transmission on the CCL3/CCR1 axis, which may be one of the reasons why this strain appeared to have the effect of worsening colitis." (PMID 36499169, 2022). "Moreover, oral cinnamon extract treatment caused a downregulation of tryptase and carboxypeptidase A3 (MC-CPA) expression and reduced expression of mast cell proteases (MC-CPA, MCP-1 and MCP-4) and pro-inflammatory mediators (CXCL8, CCL2, CCL3 and CCL4) during colitis in IL-10 knockout mice." (PMID 32962285, 2020).
colitis (continued). "Although it has been reported that CD169+ macrophages express Ccl2, Ccl7, and Ccl8 during colitis (the contribution of monocytes was not considered), and analysis of colon IBD sections has suggested CCL8 as the greatest up-regulated chemokine released from inflammatory cells." (PMID 30542349, 2018). "This suggests that macrophages and monocytes are not the key source of CCL2 release during colitis." (PMID 30542349, 2018). "Thus, further investigation is necessary to determine the synergistic role of PSMP, CCL2 and CCL7 in colitis as well as determining whether they represent the therapeutic targets." (PMID 28698550, 2017). "PSMP expression was up-regulated by colonic epithelial cells before the up-regulation of the expression of important inflammatory cytokines, including CCL2, which indicated that PSMP but not CCL2 acted first to play a key role in the initial phase of colitis in the PSMP-CCR2-monocyte axis." (PMID 28698550, 2017). "Therefore, it is possible that inhibiting the induction of CCL2 and CCL4 may reduce the migration of T cells in the colon and protect CD69 KO mice from severe colitis." (PMID 23785429, 2013). "Furthermore, VDUP1-KO mice exhibited increased mRNA expression of macrophage-attractive chemokines, including C-C motif chemokine ligand 2 (CCL2/MCP-1), C-C motif chemokine ligand 3 (CCL3/MIP1A), and keratinocyte chemoattractant (KC/CXCL1) in mice with DSS-induced colitis compared to WT mice." (PMID 37686390, 2023). "One team found that similar colitis can be induced in CCL2 KO mice and wild types, which indicated that the effects of CCR2 in colitis are independent of CCL221." (PMID 28698550, 2017). "Mice with colitis, regardless of diet, presented higher concentrations of all measured cytokines (TNF, IL-6, IL-4, IL-10, IFNy), and MCP-1/CCL2." (PMID 22073943, 2011). "We speculated that the redundancy of PSMP, CCL2 and CCL7 in colitis might result in that CCR2 but not the CCL2 is vital to the progression of colitis." (PMID 28698550, 2017).